BTG3 (BTG anti-proliferation factor 3)
Diseases named in the same sentence as BTG3 in open-access papers (continued):
Sharing a sentence is not in itself a finding about the gene and the disease.
ovarian carcinoma (7 papers, 2013 to 2024). A malignant neoplasm originating from the surface ovarian epithelium. "BTG3 expression was found to positively associate with favorable prognosis of gastric and ovarian cancers." (PMID 28407690, 2017). "BTG3 was reported to be linked with aggressiveness of ovarian carcinoma." (PMID 24147003, 2013). "A positive correlation between BTG3 expression and the post-progression survival rate was observed in all ovarian cancer patients, or G1-3, G 2-3, Grade3 or suboptimal cancer patients (p < 0.05)." (PMID 36186486, 2022). "We performed bioinformatics analysis of BTG3 expression in ovarian cancer using Bonome’s, Hendrix’s, Lu’s, Welsh’s, and TCGA’s datasets." (PMID 36186486, 2022). "The data from Kaplan-Meier plotter showed a positive relationship between BTG3 expression and the overall survival rate of the ovarian cancer patients with paclitaxel treatment (p < 0.05)." (PMID 36186486, 2022). "In our group, BTG3 hypoexpression was found to correlate with a short disease-free time and overall survival of ovarian cancer patients." (PMID 25904053, 2015). "Multivariate analysis demonstrated that BTG3 protein expression was an independent factor to indicate the favorable prognosis of ovarian carcinoma." (PMID 23657964, 2013). "According to its frequency and density, BTG3 protein expression was statistically lower in ovarian carcinoma than normal ovary and benign tumor (p < 0.05)." (PMID 23657964, 2013). "Using western blot and immunochemistry staining, BTG3 expression was reduced in ovarian carcinoma, compared with ovarian normal tissue and benign tumor, indicating that down-regulated BTG3 expression contributes to ovarian epithelial carcinogenesis." (PMID 23657964, 2013). "In contrast, our results showed BTG3 mRNA overexpression in gastric and ovarian cancers." (PMID 36186486, 2022). "Our findings suggested that BTG3 protein expression could be employed to indicate the prognosis of ovarian carcinoma patients as an independent factor." (PMID 23657964, 2013). "BTG3 expression was higher in ovarian cancer than normal mucosa regardless of histological subtyping (p < 0.05)." (PMID 36186486, 2022). "Further, the patient’s age, FIGO staging, and BTG3 protein expression (p < 0.05) but not pathological classification, differentiation residual lesion size, or serum CA125 level were independent prognostic factors for disease-free ovarian carcinomas (p > 0.05)." (PMID 23657964, 2013).
cervical cancer (5 papers, 2017 to 2025). A primary or metastatic malignant neoplasm involving the cervix. "The inhibitor of ankyrin repeats, SH3 domains, and proline-rich regions protein (iASPP), a key inducer of epithelial-mesenchymal transition (EMT), promotes cisplatin resistance by targeting FBXL5 and BTG3 through miR-20a in cervical cancer." (PMID 40534867, 2025). "Depletion of FBXL5 and B-cell translocation gene 3 (BTG3) enhances cell invasiveness and cisplatin resistance in cervical cancer." (PMID 40534867, 2025). "In the research process, it has been reported that PPP1R13L promotes EMT through the microRNA-20a-FBXL5/BTG3 signaling pathway and endows cervical cancer cells with cisplatin resistance." (PMID 32508530, 2020). "HR‐HPV infection upregulates hsa‐miR‐93‐5p expression and downregulates BTG3, hsa‐miR‐93‐5p might have a oncogenic role and function in progression of cervical cancer." (PMID 39185567, 2025). "There is a reverse relationship between miR-93 and BTG3 expression in cervical cancer cells." (PMID 32612456, 2020). "Moreover, BTG3 is considered as a tumor suppressor and its inhibition enhances the malignancy of cervical cancer cells." (PMID 32612456, 2020).
colon carcinoma (4 papers, 2014 to 2021). "According to Skrzypczak’s and TCGA datasets, BTG3 was elevated in colon carcinoma and rectal mucinous adenocarcinoma." (PMID 28922388, 2017). "Our data also found that the expression of BTG4 is downregulated in lung and colon cancers, and overexpression of BTG4 can inhibit proliferation and migration, and induce apoptosis, suggesting that similar to BTG2 and BTG3, BTG4 might also act as a potential tumor suppressor." (PMID 32093041, 2020).
renal cell carcinoma (4 papers, 2019 to 2025). "It is also noteworthy that our findings indicate that TRIM65 plays a role in the development of renal cell carcinoma by regulating BTG3 and the cell cycle." (PMID 40264575, 2025). "MiR-142-5p strengthens cell growth and migration in renal cell carcinoma, while miR-93 desensitizes esophageal cancer to radiotherapy by targeting BTG3." (PMID 36186486, 2022). "It has been shown that GE can reactivate methylation-silenced tumor suppressor BTG3 gene by CpG demethylation and inhibition of DNMT and MBD2 activity in HEK- 293 renal cell carcinoma." (PMID 31030484, 2019).
lymph node metastasis (3 papers, 2015 to 2022). "The relapse-free survival rate of the cancer patient with or without lymph node metastasis was lower in the groups of high BTG3 expression than its low expression (p < 0.05, data not shown)." (PMID 36186486, 2022).
metastatic carcinoma (3 papers, 2013 to 2017). A carcinoma which has spread from the original site of growth to another anatomic site. "We measured the expression of BTG3 mRNA in ovarian normal tissue (n = 17), benign tumor (n = 12), borderline tumor (n = 6), and primary (n = 65) and metastatic carcinoma (n = 21) by real-time RT–PCR." (PMID 23657964, 2013). "BTG3 mRNA expression level was higher in ovarian normal tissue and benign tumor, and lower in borderline tumor and primary and metastatic carcinoma (p < 0.05)." (PMID 23657964, 2013). "The BTG3 mRNA expression level was higher in ovarian normal tissue and benign tumors than that in borderline, primary, and metastatic carcinoma (p < 0.05), and was negatively correlated with dedifferentiation and FIGO staging of EOC (p < 0.05)." (PMID 23657964, 2013). "BTG3 expression was positively observed in the cytoplasm of superficial mucosa, deep propria glands, well-, moderately-, poorly-differentiated, mucinous, signet ring cell carcinoma and metastatic carcinoma in lymph node." (PMID 25904053, 2015). "Here, we found that BTG3 protein was mainly localized in the cytoplasm of superficial mucosa, infiltrating inflammatory cells, deep propria glands, fundic glands, primary and metastatic cancers." (PMID 25904053, 2015). "BTG3 expression was detectable in normal ovary tissue (78.6 %, 22/28), benign tumor (80.0 %, 12/15), borderline tumor (41.7 %, 10/24), carcinoma (51.0 %, 127/249), and metastatic carcinoma in omentum (50.0 %, 24/48), respectively." (PMID 23657964, 2013). "BTG3 expression was detectable in colorectal NNM (46.3%, 220/475), adenoma (57.9%, 73/126), primary cancer (82.0%, 396/484), and metastatic cancer in lymph node (80.0%, 120/150) and liver (81.0%, 17/21) respectively." (PMID 28407690, 2017). "BTG3 expression was detectable in gastric non-neoplastic mucosa (83.3%, 474/569), primary cancer (33.1%, 203/613), and metastatic cancer in lymph node (31.7%, 57/180), respectively." (PMID 25904053, 2015).
renal carcinoma (3 papers, 2013 to 2024). A carcinoma arising from the epithelium of the renal parenchyma or the renal pelvis. "In human, BTG3 expression is down-regulated in lung, prostate, or renal cancer tissues and cells, and induced by genistein and 5-aza-2′-deoxycytidine, suggesting silenced BTG3 expression is attributable to its epigenetic methylation." (PMID 23657964, 2013). "Furthermore, we found that ectopic overexpression of BTG3 eliminated the acceleration of TRIM65 on the anchorage-independent growth abilities of renal cancer cells in soft agar assays." (PMID 38777825, 2024). "In renal cancer, GEN increases histone acetylation by enhancing HAT activity and causes acetylation of histones 3 and 4, dimethyl-H3K4 and trimethyl-H3K4 near the transcription start site at the BTG3 gene promoter." (PMID 29899271, 2018).
autism (2 papers, 2016 to 2018). Persistent deficits in social interaction and communication and interaction as well as a markedly restricted repertoire of activity and interest as well as repetitive patterns of behavior. "BTG3 has also been linked with autism because of its role in cellular apoptosis and responses to redox changes." (PMID 31061677, 2018). "Deletions of BTG3 have been reported in a subset of patients with autism characterized by developmental regression and in patients with neurodevelopmental delay (Decipher 285691, 285987, 288573, 291626, and 300775)." (PMID 27625702, 2016).
lobular breast carcinoma (2 papers, 2017 to 2022). "BTG3 was decreased in invasive ductal and lobular breast carcinoma in studies from Finak and Turashvili." (PMID 28922388, 2017). "TCGA database showed a higher BTG3 expression in invasive ductal than lobular carcinoma (p < 0.05)." (PMID 36186486, 2022).
skin cancer (2 papers, 2024 to 2025). "BTG3 knockout keratinocytes induce the development of skin cancer by activating NF-κB in the mouse DMBA/TPA skin cancer induction model." (PMID 40169858, 2025). "Here, we dissected the role of BTG3 in the functional interplay between keratinocytes and adipocytes, with a possible connection to neoplastic transition in skin cancer." (PMID 38714880, 2024). "Thus, our findings showcased the role of BTG3 in guarding the interplay between keratinocytes and adjacent adipocytes, and identified the underlying neoplastic molecular mediators that may serve as possible targets in the treatment of skin cancer." (PMID 38714880, 2024).
squamous cell carcinoma (2 papers, 2022 to 2024). A carcinoma arising from squamous epithelial cells. "Pulmonary adenocarcinoma patients had a higher BTG3 mRNA expression than squamous cell carcinoma patients." (PMID 36186486, 2022). "In TCGA database, BTG3 expression was higher in female than male cancer patients, T1-2 than T3-4, and adenocarcinoma than squamous cell carcinoma patients (p < 0.05)." (PMID 36186486, 2022). "Here, we demonstrated that BTG3 levels are downregulated in basal cell carcinoma and squamous cell carcinoma compared to normal skin tissue, and Btg3 knockout in mice augmented the development of papilloma in a mouse model of DMBA/TPA-induced skin carcinogenesis." (PMID 38714880, 2024).
triple-negative breast carcinoma (2 papers, 2022 to 2023). An invasive breast carcinoma which is negative for expression of estrogen receptor (ER), progesterone receptor (PR), and human epidermal growth factor receptor 2 (HER2). "LncRNA ASBEL has been identified as oncogene and an anti-sense transcript of tumor-suppressor gene of BTG3 in triple-negative breast cancer (TNBC)." (PMID 37904215, 2023).
adenoma (1 paper, 2017). A neoplasm arising from the epithelium. "Then, we used Gaedcke's, Hong's, Skrzypczak's and TCGA's dataset to perform bioinformatical analysis and found that BTG3 mRNA expression was higher in colorectal normal mucosa than adenoma or cancer (p<0.05)." (PMID 28407690, 2017). "BTG3 protein was distributed in the cytoplasm of colorectal epithelium, infiltrating inflammatory cells, macrophages, hepatocytes, lymphoid follicle, adenoma, and cancers." (PMID 28407690, 2017).
adenovirus infection (1 paper, 2019). "Persistent adenovirus infection of B-lymphocytes has been shown to significantly down-regulate several cellular genes (BBS9, BNIP3, BTG3, CXADR, SLFN11, and SPARCL -), however, none are reported to obviously function in the regulation of metabolism." (PMID 31864392, 2019).
borderline epithelial ovarian tumors (1 paper, 2013). "The expression of BTG3 protein was examined by immunohistochemistry on tissue microarrays containing ovarian normal tissue, benign and borderline epithelial ovarian tumors, and EOCs." (PMID 23657964, 2013).
brain cancer (1 paper, 2017). A primary or metastatic malignant neoplasm affecting the brain. "With respect to brain cancer, increased TOB1-2 and BTG3 revealed poor prognosis, while higher BTG2 was related to better prognosis." (PMID 28922388, 2017).
cervical adenocarcinoma (1 paper, 2017). An adenocarcinoma arising from the cervical epithelium. "Furthermore, we provided the first evidence that iASPP stimulates EMT and induces cisplatin resistance in both cervical adenocarcinoma cell line HeLa and cervical squamous cell carcinoma cell line SiHa, through regulating the downstream miR-20a-FBXL5/BTG3 signaling pathway." (PMID 28399926, 2017).
Cirrhosis (1 paper, 2013). A chronic disorder of the liver in which liver tissue becomes scarred and is partially replaced by regenerative nodules and fibrotic tissue resulting in loss of liver function. "No obvious difference of BTG3 expression was seen between HCC tissues with cirrhosis and those without cirrhosis (P<0.001)." (PMID 24147003, 2013).
developmental delay (1 paper, 2023). "Consistently, deletions and mutations in BTG3 and HECW2 have been associated with developmental delay and epilepsy." (PMID 36649033, 2023). "Interestingly, mutations in and deletions of BTG3 and HECW2 have been associated with cases of human epilepsy and developmental delay." (PMID 36649033, 2023).
diabetes (1 paper, 2023). "Moreover, exposure to diabetes reverses normally anti-correlated to somite-correlated expression of Banp, which associates with BTG3 in an anti-proliferative nuclear complex." (PMID 37928898, 2023).
esophageal cancer (1 paper, 2017). A primary or metastatic malignant neoplasm involving the esophagus. "BTG3 was also shown to suppress proliferation and invasion of gastric and esophageal cancer cells." (PMID 28399926, 2017).
Intellectual disability (1 paper, 2016). "RBM11 was deleted in 10 out of 15 cases with the most severe phenotype (intellectual disability), whereas BTG3 in all of these cases." (PMID 27625702, 2016).
Lewis lung carcinoma (1 paper, 2020). "We then injected luciferase-expressing Lewis lung carcinoma cells (LLC1-Luc) subcutaneously into either WT or their Btg3−/− littermates and compare tumor growth." (PMID 33311481, 2020).
mucinous adenocarcinoma (1 paper, 2018). An invasive adenocarcinoma composed of malignant glandular cells which contain intracytoplasmic mucin. "More important, the majority of adenocarcinoma tissues showed significantly higher cytoplasmic expression of BTG3 than mucinous adenocarcinoma." (PMID 29270670, 2018).
nasopharyngeal carcinoma (1 paper, 2022). A carcinoma arising from the nasopharyngeal epithelium. "Furthermore, through its target gene, BTG3 (BTG anti-proliferation factor 3), and activation of autophagy-regulating MAPK signaling, its overexpression inhibits autophagy and promotes the malignant phenotype of nasopharyngeal cancer cells." (PMID 35885944, 2022).
non-melanoma skin carcinoma (1 paper, 2024). "Collectively, these data support the notion that BTG3 functions as a tumor suppressor in non-melanoma skin cancer and likely in HNSCC." (PMID 38714880, 2024).
ovarian benign tumor (1 paper, 2013). "BTG3 was lower in EOCs than in normal ovary tissues (p = 0.002) and benign ovarian tumors (p = 0.046)." (PMID 23657964, 2013). "By western blot assays, we measured BTG3 protein expression in normal ovary tissues (n = 9), benign ovarian tumors (n = 10), and EOCs (n = 59)." (PMID 23657964, 2013). "BTG3 protein distributed in the cytoplasm of normal ovary tissue, ovarian benign tumor, and EOCs." (PMID 23657964, 2013).
papilloma (1 paper, 2024). A benign epithelial neoplasm that projects above the surrounding epithelial surface and consists of villous or arborescent outgrowths of fibrovascular stroma. "The difference in susceptibility became more pronounced in aged mice in which BTG3 KO mice had apparent thicker skin adipose tissue and developed papillomas significantly earlier and larger in size than the WT." (PMID 38714880, 2024). "We observed that papillomas developed and grew to a larger size on the skin of Btg3−/− mice than on the skin of WT mice, suggesting that BTG3 loss may promote skin carcinogenesis." (PMID 38714880, 2024).
Portal vein thrombosis (1 paper, 2013). Thrombosis of the portal vein and/or its tributaries, which include the splenic vein and the superior and inferior mesenteric veins. "From univariate analysis, the significant prognostic factors were BTG3 expression, portal vein thrombosis, differentiation, distant metastasis, disseminationand relapse (P<0.05)." (PMID 24147003, 2013).
pulmonary stenosis (1 paper, 2018). "Considering patient S3 displayed pulmonary stenosis while patient S1 did not, and the extra duplicated region of S3 includes BTG3, this gene could potentially contribute to this clinical distinction." (PMID 31061677, 2018).
rheumatoid arthritis (1 paper, 2024). A chronic, systemic autoimmune disorder characterized by inflammation in the synovial membranes and articular surfaces. "Besides, in the rheumatoid arthritis, the AUC values for CEBPA, CEACAM1, BTG3, and IL1R1 were 0.609, 0.730, 0.686, and 0.608, respectively and diagnostic model achieved a high AUC of 0.844 on this cohort." (PMID 39113685, 2024).
schizophrenia (1 paper, 2023). A major psychotic disorder characterized by abnormalities in the perception or expression of reality. "Previous studies have shown that genes such as PMAIP1, DNAJC3, DFFA, and BTG3 are involved in apoptosis, but their specific mechanism of action in schizophrenia needs to be further explored." (PMID 37383091, 2023).
squamous cell lung carcinoma (1 paper, 2017). A carcinoma arising from squamous bronchial epithelial cells. "In Talbot’s dataset, it was extracted that BTG3 was elevated in squamous cell lung carcinoma compared to normal group." (PMID 28922388, 2017).